LINC01554 (long independently transcribed non-coding RNA 1554)
Synonyms: C5orf27; FLJ38821; FIS
Gene: Long non-coding RNA gene on chromosome 5 (95,838,244 to 95,860,141, forward strand). Ensembl gene ENSG00000236882.
Diseases named in the same sentence as LINC01554 in open-access papers:
LINC01554 is named in the same sentence as 7 diseases in open-access papers, as found by Europe PMC text mining. Sharing a sentence is not in itself a finding about the gene and the disease. The quoted sentences say what the papers report.
hepatocellular carcinoma (3 papers, 2021 to 2022). A malignant tumor that arises from hepatocytes. "For example, expression of LINC01554 in hepatocellular cancer was lower in comparison to normal tissue, and the reduced expression of LINC01554 was in correlation with the advanced tumor stage, metastasing, tumor recurrence and shorter overall survival." (PMID 36230605, 2022). "LINC01554 was a recently identified lncRNA whose upregulation was firstly confirmed in hepatocellular carcinoma according to a previously published microarray analysis." (PMID 34422133, 2021). "lncRNA LINC01554 (LINC01554), a recently identified tumor-related lncRNA, has been reported to be dysregulated in several types of neoplasms, such as esophageal cancer, cervical cancer, and hepatocellular carcinoma." (PMID 34422133, 2021). "Importantly, they showed that knockdown of LINC01554 suppressed the proliferation and metastasis via suppressing the Akt/mTOR signaling pathway, suggesting LINC01554 as an oncogenic lncRNA in hepatocellular carcinoma." (PMID 34422133, 2021). "The expression of long intergenic nonprotein coding RNA 1554 (LINC01554), located on chromosome 5q15, was found to be downregulated in hepatocellular carcinoma (HCC) where it was involved in cancer progression." (PMID 35845928, 2022).
esophageal squamous cell carcinoma (1 paper, 2022). Esophageal squamous cell carcinoma (ESCC) is a type of esophageal carcinoma (EC) that can affect any part of the esophagus, but is usually located in the upper or middle third. "A role of LINC01554 in tumorigenesis was further corroborated a recent mechanistic study in showing that LINC01554 promotes metastasis of esophageal squamous cell carcinoma." (PMID 36230605, 2022).
fibrosis (1 paper, 2017). the formation of excess fibrous connective tissue in an organ or tissue in a reparative or reactive process. "Decreasing expression of LINC01554 (also known as C5orf27 or FLJ38821) was associated with advancing fibrosis in NAFLD patients." (PMID 28955037, 2017).
liver cancer (1 paper, 2025). An epithelial or non-epithelial malignant neoplasm that arises from the liver. "The results confirmed that P. grandiflorum polysaccharides promote apoptosis in liver cancer cells by enhancing the expression of LINC01554 (a long non-coding RNA), thereby inhibiting the progression of liver cancer." (PMID 41220717, 2025).
tumor (7 papers, 2020 to 2025). "Downregulation of LINC01554 is associated with adjacent organs invasion, tumor size, staging and higher risks of tumor recurrence." (PMID 40596757, 2025). "Similarly, reduced LINC01554 expression and its association with advanced tumor stage and reduced overall survival was characteristic of epithelial ovarian cancer." (PMID 36230605, 2022). "We suggest low expression levels of LINC01554 observed in different TCGA tumor datasets also reflect some general background LINC01554 amounts, as this lncRNA is downregulated in HCC and CCA." (PMID 40596757, 2025). "Like our analysis, LINC01554 may function as a tumor suppressor gene, while the CYTOR and BSG-AS1 may act as oncogenes." (PMID 35840618, 2022). "LINC01554 is a novel tumor suppressor that could suppress tumorigenicity in HCC via Akt/mTOR signaling pathway." (PMID 35840618, 2022). "By comparing the patients in high and low LINC01554 expression groups, we found that patients in low LINC01554 expression group exhibited significantly higher incidence of huge (tumor diameter >5cm) and multiple lesions than that in high expression group (P<0.05)." (PMID 32231743, 2020). "Thus, it indicated that LINC01554 functioned as a tumor suppressor in the progress of HCC." (PMID 32231743, 2020). "For example, the expression of LINC01554 in HCC is significantly downregulated, and its expression has a significant relationship with the tumor size, multiple lesions, TNM stage, tumor recurrence rate, and long-term survival rate of liver cancer patients." (PMID 33062024, 2020). "Negative association between LINC01554 and miR‐365a‐3p expression was found in HCC tumor samples as well." (PMID 40596757, 2025).
cancer (5 papers, 2019 to 2024). A tumor composed of atypical neoplastic, often pleomorphic cells that invade other tissues. "However, the expression of LINC01554 has been associated with other human cancers." (PMID 36230605, 2022). "These included the cancer-related lncRNAs DLEU2, SNHG7, and LINC01554 (found in only polysomal and common fractions, respectively), the recently re-annotated lncRNA ENS00000269825 (common), the novel lncRNA ENS00000267882 (only total), and the lncRNA DANCR (common)." (PMID 38396700, 2024). "LINC01554 promotes proteasomal degradation of PKM2, an important enzyme at the late stage of glycolysis, and inhibits the Akt/mTOR signaling pathway, one of the key signalling pathways that mediates cellular biosynthesis and aerobic glycolysis in cancer cells." (PMID 33652661, 2021). "Here, we found that G3BP2 was protected by LINC01554 from ubiquitin-mediated protein degradation and stabilized HDGF mRNA transcripts to drive ESCC metastasis, which has not yet been reported during cancer progression." (PMID 34782720, 2022).
LINC01554 also shares sentences with these, for which no sentence is quoted: esophageal cancer (1 paper).